TNF (tumor necrosis factor)
Diseases named in the same sentence as TNF in open-access papers (continued):
Sharing a sentence is not in itself a finding about the gene and the disease.
intestinal inflammation (60 papers, 2011 to 2026). "Intestinal inflammation is associated with several diseases, and the production of interleukin-8 (IL-8) in intestinal epithelial cells induced by tumor necrosis factor (TNF)-α has an important role in inflammatory reaction." (PMID 38940894, 2024). "Moreover, IL-6 can induce the proliferation of Th17 cells, which can secrete pro-inflammatory cytokines, such as IL-17 and TNF-α, to play pathogenic roles in intestinal inflammation." (PMID 33967768, 2021). "Stress from separating piglets from their sows, along with dietary and environmental changes, can induce transient intestinal inflammation in piglets, characterized by increased pro-inflammatory cytokines TNF-α, IL-6, and IL-1β." (PMID 40336817, 2025). "Meanwhile, the levels of inflammatory cytokines (e.g., IL-6, IL-1β and TNF-α) were elevated, indicating the presence of intestinal inflammation." (PMID 40427600, 2025). "Proinflammatory cytokines, including TNF-α, IL-6, IL-1β, and IL-17, play an important role in drug-induced and spontaneous intestinal inflammation." (PMID 37660913, 2023). "Kaempferol dramatically reduced the extensive production of TNF-α and IL-6 in lipopolysaccharide-induced intestinal inflammation in rats." (PMID 36080365, 2022). "Contrary to the anti-inflammatory cytokines, IL-1β, IL-6, and TNF-α, as pro-inflammatory cytokines which have been reported in the intestinal inflammation occurrence, were dose-dependently decreased by SSPs administration." (PMID 35359717, 2022). "Intestinal inflammation involves immune cells of both the innate and adaptive immune systems, and is characterized by marked increases in pro-inflammatory cytokines IL-1β, TNF-α, IL-12, IL-17, IL-1α and INF-γ." (PMID 32998266, 2020). "A recent study in patients with IBD showed that Sb reduced TNF-α production and significantly inhibited T-cell proliferation induced by intestinal inflammation." (PMID 22848391, 2012). "At the same time, intestinal pathogens can invade intestinal epithelial cells, activate the intracellular signal transduction system, trigger the host immune response, stimulate the secretion of TNF-α, IL-6, and other inflammatory cytokines and mRNA expression, and induce intestinal inflammation." (PMID 39852407, 2025). "Although 4-methylesculetin was not reported as an inhibitor of the NF-κB signaling pathway, a reduction of pro-inflammatory cytokines production, such as IL-1β, IL-6, IL-17, and TNF-α was described in experimental models of intestinal inflammation at same doses." (PMID 37111267, 2023). "The intestine is one of the targets for Cd and its exposure may induce intestinal inflammation, and increase the levels of inflammatory factors such as IL-6 and TNF-α in the blood and intestine." (PMID 37565077, 2023). "Intestinal inflammation is related to higher TNF-α, IL-1β, and IL-6 levels." (PMID 37111225, 2023). "We mimicked LPS-induced intestinal inflammation that could demonstrate the IAP-mediated decrease in the LPS-induced cytokine production of TNF-α and IL-6." (PMID 35958560, 2022). "The activation of the pro-inflammatory genes in IECs in response to challenges by bacterial products such as lipopolysaccharide (LPS) or pro-inflammatory cytokines such as tumor necrosis factor (TNF)-α is associated with acute and chronic intestinal inflammation." (PMID 31035617, 2019). "NF-κB proteins are a major family of transcription factors, composed of subunits of the Rel family, p50 and p65, which play a key role in the regulation of proinflammatory gene transcription such as IL-1β, IL-6, TNF-α, Cox-2, iNOS, and adhesion molecules in the process of intestinal inflammation." (PMID 29853790, 2018). "Additionally, cytokines and other inflammatory mediators including IL-1 and 6 and tumor necrosis factor (IL-1, IL-6, TNF) produced in response to intestinal inflammation can affect the skin, exacerbating existing conditions or triggering new dermatological issues." (PMID 39529755, 2024).
intestinal inflammation (continued). "The reason might be as follows: (a) MALT1 activated NF‐κB signaling pathway; meanwhile the activation of NF‐κB pathway was correlated with the secretion of various inflammatory cytokines (including IL‐1, IL‐6, TNF‐α, etc.)as well as the severity of intestinal inflammation." (PMID 34997981, 2022). "Changes of IL-6 and TNF-α level may be closely associated with the attack, development and even recovery of diarrhea, and the moderate rise of TNF-α and IL-6 is conductive to the control over the body inflammatory reaction as well as the prevention from further development of gastroenteritis." (PMID 28798800, 2017). "In a 1-year study in Mongolia, IL-6 and TNF-alpha levels were studied in infants with benign seizures and acute gastroenteritis and compared with those without seizures and gastroenteritis." (PMID 39062898, 2024). "In the DSS-model of intestinal inflammation in mice osthole showed protective effects on intestinal inflammation improving clinical parameters and histological damages as well as reducing MPO activity and downregulating colon TNF-α and serum TNF-α levels." (PMID 33467396, 2021). "Recent studies have shown that physiological concentrations of IL-1β and TNF-α significantly increase intestinal epithelial TJ permeability, and inhibiting the IL-1β-induced increase in intestinal TJ permeability prevents sodium dextran sulfate (DSS)-induced intestinal inflammation." (PMID 37523400, 2023). "Animal studies have suggested that lycopene could not only suppress the expression of pro-inflammatory factors like IL-1β, IL-6, IL-8 and TNF-α, but also stimulate the production of anti-inflammatory cytokines (such as TGF-β, IL-10), so as to reduce intestinal inflammation." (PMID 37608273, 2023). "Additional predictive analysis of regulatory genes showed that the activation of gastroenteritis by RYGB was independent of classical nuclear factor kappa B (NFkB) activation and tumor necrosis factor alpha (TNF-α) expression." (PMID 30944407, 2019).
knee osteoarthritis (60 papers, 2013 to 2026). "Focusing on genes associated with the TNF signaling pathway, this study aims to explore their mechanisms roles in knee osteoarthritis." (PMID 40826778, 2025). "These genes were consistently selected by both algorithms, highlighting their potential importance in the development and progression of knee osteoarthritis and their strong association with the TNF signaling pathway." (PMID 40826778, 2025). "Induction of knee osteoarthritis caused a loss in muscle coordination, knee swelling, elevations in the inflammatory mediators (TNF-α & TGF-β1), and the oxidative stress markers (MMP-13 & NOX-4) in joint tissues." (PMID 37878123, 2023). "Correlation between TNF-α G-308A gene polymorphism and knee osteoarthritis risk." (PMID 34735544, 2021). "The purpose of this investigation was to identify if serum IL-10 and TNF-α concentrations and their ratio (i.e., IL-10/TNF-α) are altered in subjects predisposed to developing knee osteoarthritis following ligamentous trauma and in those with severe knee osteoarthritis." (PMID 33469085, 2021). "In another study, 50 g twice/day of freeze-dried strawberries for 12 weeks led to a reduction in TNF-α levels in obese adults with knee osteoarthritis, while IL-19 levels remained unchanged." (PMID 40944222, 2025). "Unbalanced remodeling of the articular cartilage driven by inflammatory mediators, including IL-1beta, IL-6, and TNF-α, is a significant contributing factor to the development and progression of knee osteoarthritis." (PMID 40636390, 2025). "Knee osteoarthritis is characterized as an inflammatory osteoarticular condition, with interleukin-1β (IL-1β) and TNF-α recognized as key inflammatory mediators in its pathogenesis." (PMID 41163114, 2025). "In mice, KAG-308 (EP4 selective agonist) administration reduces chondrocyte hypertrophy and TNF secretion, leading to the suppression of knee osteoarthritis." (PMID 39458926, 2024). "This is consistent with the results of 10.6 μm laser moxibustion on IL6, TNFα and IL1β in knee osteoarthritis animal models." (PMID 37593350, 2023). "PRP treatment for knee osteoarthritis effectively lowers the concentrations of inflammatory factors IL-6, IL-1β, TNF α, IL-17A, and IL-10, significantly alleviating knee joint pain and enhancing joint functionality." (PMID 37869166, 2023). "Another evidence indicated that l-car supplementation has beneficial effects on reducing TNF-α levels in knee osteoarthritis patients." (PMID 37363159, 2023). "Intra-articular autologous injection of BMSCs into the knee joint of patients with knee osteoarthritis reduces serum TNF-α and IL-6 levels and significantly improves pain and clinical scores compared with endoscopic synovectomy and hyaluronic acid injection." (PMID 36766847, 2023). "As a result, the findings suggest that combining flurbiprofen perioperatively with arthroscopic debridement in individuals with knee osteoarthritis is helpful, especially for reducing the expression of IL-1β, TNF-α, COX-2, and other inflammatory factors." (PMID 35813424, 2022). "Some reports believe that PRP can inhibit inflammatory factors such as tumor necrosis factor-α and interleukin and reduce the inflammatory responses in knee osteoarthritis." (PMID 35656456, 2022). "Results from our study clearly showed that gonarthrosis patients with DM had significantly lower systemic values of proinflammatory cytokines TNF-α, IL-6, IL-12, IFN-γ, and IL-17." (PMID 36141752, 2022). "For example, electroacupuncture relieves pain in patients with knee osteoarthritis, partly by reducing pro-inflammatory factors tumor necrosis factor-alpha (TNF-α) and Interleukin 1 beta (IL-1β)." (PMID 36337711, 2022). "Specifically, serum IL-10 and TNF-α concentrations and the serum IL-10/TNF-α ratio are compared between moderate (KL = 3, ≤ 50% joint space narrowing) and severe (KL = 4, > 50% joint space narrowing) knee osteoarthritis." (PMID 33469085, 2021).
knee osteoarthritis (continued). "Differentiating moderate from severe knee osteoarthritis, however, revealed a lower serum IL-10 concentration and serum IL-10/TNF-α ratio with severe knee osteoarthritis." (PMID 33469085, 2021). "These core target genes are involved in signaling pathways related to cartilage degeneration of knee osteoarthritis such as TNF signaling pathway and PI3K-Akt signaling pathway." (PMID 34273999, 2021). "Future research assessing the clinical utility of the serum IL-10/TNF-α ratio and other cytokine and cytokine ratios as systemic biomarkers capable of phenotypically differentiating the severity in knee osteoarthritis is warranted." (PMID 33469085, 2021). "Then, our data showed that umbilical cord MSCs reduced NO, IL-6, and TNF-α in serum and joint fluid and attenuated the inflammatory response in an animal model of knee osteoarthritis." (PMID 35095776, 2021). "We showed previously that adjunct resveratrol supplementation with NSAID reduces pain and inflammation reflected as a significant reduction of serum levels of the proinflammatory markers including IL-6, IL-1β, and TNF-α in patients with knee osteoarthritis." (PMID 34805399, 2021). "Chen found that thunder-fire moxibustion effectively reduced the contents of TNF-α and IL-1β in serum in the rat model of knee osteoarthritis, thereby inhibiting inflammatory response and alleviating symptoms." (PMID 32148545, 2020). "In this study, we investigated the ability of CSF from patients diagnosed with knee osteoarthritis suffering from chronic pain, to trigger the release of pro-inflammatory cytokines, IL-6, IL-1beta and tumour necrosis factor alpha (TNF-α) from T98G." (PMID 32213162, 2020). "Tumor necrosis factor alpha (TNF-α) mediated inflammation has been implicated, in knee osteoarthritis, despite being a predominantly degenerative condition." (PMID 32664142, 2020). "Elevated levels of serum TNF-α are observed in patients with knee osteoarthritis, which, similar to COMP, also increase with the severity of disease." (PMID 30105061, 2018). "Kellgren-Lawrence grade, physical exercise, all anthropometric measurements (especially waist circumference), tumor necrosis factor α, and high levels of leptin, resistin, and ostepontin were related to knee osteoarthritis severity." (PMID 27629533, 2016). "TNF has been compared to other proinflammatory cytokines and shown to be elevated in elderly patients with knee osteoarthritis." (PMID 25821631, 2015). "A randomized controlled trial demonstrated that a 4-week course of TFM treatment could alleviate knee osteoarthritis symptoms by reducing IL-6 and tumor necrosis factor levels." (PMID 40134594, 2025). "Therefore, it is of interest to evaluate the associationbetween serum vitamin D levels, pro-inflammatory cytokines (IL-6, TNF-α), and functional status in patients with knee osteoarthritis(OA)." (PMID 41170094, 2025). "In the context of knee osteoarthritis, inflammatory cytokines such as IL-6 and TNF-α may affect bone marrow function and iron metabolism, thereby influencing RDW levels." (PMID 40755482, 2025). "An individual’s milieu of inflammatory cytokines may contribute to the development and severity of knee osteoarthritis, where higher concentrations of serum TNF-α and macrophage migration inhibitory factor (MIF) are associated with increased severity." (PMID 40219030, 2025). "From this experiment, our findings suggest that the YTPS ethanolic extract exerts anti-inflammatory properties through the reduction in IL-6 and TNF-α secretion, the two main pro-inflammatory cytokines found at high levels while the inflammation of knee osteoarthritis occurs." (PMID 39204123, 2024). "Interestingly, a previous study unveiled increased Gal‐3 mRNA expression induced by TNF‐α in knee osteoarthritis synoviocytes." (PMID 39230472, 2024).
knee osteoarthritis (continued). "Knee osteoarthritis (KOA) and certain inflammatory cytokines (such as interleukin 1 [IL-1] and tumor necrosis factor alpha [TNF-a]) are related; however, the causal relationship remains unclear." (PMID 38698846, 2024). "TNF-α is a pro-inflammatory cytokine that can increase osteoclast activity and inhibit osteoblast activity, inhibit the synthesis of proteoglycans and cartilage collagen, and is involved in the occurrence and development of knee osteoarthritis." (PMID 35813424, 2022). "Based on these findings, we conclude that serum IL-10 concentrations are compromised without significant serum TNF-α deviations in subjects predisposed to developing knee osteoarthritis following ligamentous trauma and in subjects with severe radiographic evidence of knee joint space narrowing." (PMID 33469085, 2021). "Additionally, apelin, tumor necrosis factor-alpha (TNF-α), and interleukin (IL)-6 may be involved in the therapeutic effect of electroacupuncture (EA) on knee osteoarthritis, a common cause of joint pain." (PMID 32231577, 2020). "Systemic values of proinflammatory TNF-α, IL-6, IL-12, IFN-γ, IL-17, and Gal-3 in gonarthrosis patients with DM were significantly lower than in gonarthrosis patients without DM." (PMID 36141752, 2022). "The results of the study suggest that bioavailable turmeric extract is as effective as paracetamol in reducing pain and other symptoms of knee osteoarthritis and found to be safe and more effective in reducing CRP and TNF-α." (PMID 33516238, 2021). "In advanced knee osteoarthritis (grade IV), co-immunolabelling for FKBP51 and TNFα at a medium-high intensity, was found in most cells of synovial tissue, including vessels, synovial membrane, and infiltrating cells." (PMID 34571845, 2021). "Studies show that an increase in IL-10 may be transient, whereas TNF-α may be elevated chronically, and there is a possible role of low IL-10 to TNF-α ratio, contributing to severe knee osteoarthritis." (PMID 37371414, 2023). "In our study, lower values of TNF-α, IL-6, and IFN-γ in patients with gonarthrosis and DM may explain the lower values of the WOMAC index." (PMID 36141752, 2022). "Results from this analysis indicate that serum IL-10 concentrations and the serum IL-10/TNF-α ratio are lower with severe knee osteoarthritis while the serum TNF-α concentration is not significantly different between disease severity subgroups." (PMID 33469085, 2021). "We hypothesized that serum IL-10 and TNF-α concentrations are higher following an anterior cruciate ligament injury and that the serum IL-10/TNF-α concentration ratio is lower with severe knee osteoarthritis." (PMID 33469085, 2021). "Serum IL-10 and the serum IL-10/TNF-α ratio were significantly lower while serum TNF-α was not significantly perturbed with severe compared to moderate knee osteoarthritis (i.e., Kellgren-Lawrence grade 4 vs. 3, respectively)." (PMID 33469085, 2021). "In individuals with knee osteoarthritis, supplementation with creatine (20 g/d for one week followed by 5g/d for 11 weeks) does not affect C-reactive protein, tumor necrosis factor-α (TNF-α), interleukin (IL)-1β, IL-6 or s100 A8/A9 concentrations in the systemic circulation." (PMID 40219030, 2025). "IL-10/TNF-α (p = 0.001), IL-10/IL-6 (p = 0.001), and IL-10/IL-12 (p = 0.001) were significantly higher, while IL-10/IL-17 (p = 0.001) ratio was significantly lower in gonarthrosis patients with DM compared to gonarthrosis patients without DM." (PMID 36141752, 2022). "Significantly higher Gal-3/TNF-α (p = 0.001), Gal-3/IL-6 (p = 0.004), and Gal-3/IL-12 (p = 0.001) and lower Gal-3/IL-17 (p = 0.001) were detected in gonarthrosis patients with DM compared to gonarthrosis patients without DM." (PMID 36141752, 2022). "We observed lower serum levels of Gal-3 as well as TNF-α, IL-6, IL-12, IFN-γ, and IL-17 in gonarthrosis patients with DM compared to gonarthrosis patients without DM." (PMID 36141752, 2022).
knee osteoarthritis (continued). "Significantly lower concentration of TNF-α (p = 0.001), IL-6 (p = 0.001), IL-12 (p = 0.001), IL-17 (p = 0.001), IFN-γ (p = 0.014), and Gal-3 (p = 0.040) was found in gonarthrosis patients with DM compared to gonarthrosis patients without DM." (PMID 36141752, 2022). "Similarly, we previously observed significant associations between the endo-EV and exo-EV concentrations of TNF-α, IL-6, and IFN-γ in plasma of patients with knee osteoarthritis, but not IL-1β." (PMID 38633262, 2024). "As our study showed a lower level of Gal-3 as well as TNF-α, IL-6, IL-12, IFN-γ, and IL-17 in gonarthrosis patients with DM, we believe that the lack of these cytokines caused intense tissue damage and slower tissue repair, which is reflected through a higher WOMAC score." (PMID 36141752, 2022). "Serum IL-10 concentrations and the serum IL-10/TNF-α ratio were lower and serum TNF-α was not significantly different with a KL grade of 4 compared to a grade 3, implying a compromise in the circulating anti-inflammatory status with severe knee osteoarthritis." (PMID 33469085, 2021).